TTF1 (transcription termination factor 1)
Diseases named in the same sentence as TTF1 in open-access papers (continued):
Sharing a sentence is not in itself a finding about the gene and the disease.
adenocarcinoma (continued). "TTF-1 is a nuclear protein involved in the development of the lungs and is highly specific for adenocarcinomas." (PMID 39070460, 2024). "The reported specificity of TTF1 ranges from 83 to 100%.12, 13, 14, 15, 16, 17, 18In this study, specificity of TTF1 was 96.75% for adenocarcinomas." (PMID 39584166, 2024). "Specificity of Napsin A varies from 83 to 100%.13, 14, 15, 18We obtained 81.08% specificity for adenocarcinoma which was lower than TTF1." (PMID 39584166, 2024). "We found that the majority of lung tumors displayed adenocarcinoma pathology and were positive for TTF1 staining." (PMID 37051524, 2023). "TTF-1 expression in adenocarcinoma is particularly important in distinguishing pulmonary adenocarcinoma from non-pulmonary adenocarcinoma." (PMID 37675165, 2023). "TTF-1 has been observed in lung tumors in alveolar adenoma, adenocarcinoma, carcinoid tumor, large cell neuroendocrine carcinoma, and small cell carcinoma." (PMID 37675165, 2023). "The best-studied markers, which today represent the standard in the diagnosis of LC, are TTF-1 and p63, with high specificity and sensitivity in differentiating squamous from primary and secondary adenocarcinomas." (PMID 36766867, 2023). "In CK7 + /CK20 − male and in CK7 + /CK20 − /ER − female adenocarcinomas, TTF1 and/or napsin A were the first option, to exclude the lung origin." (PMID 36346458, 2023). "Percutaneous biopsy of the lung mass demonstrated poorly differentiated adenocarcinoma with TTF‐1 expression consistent with lung origin, but insufficient tissue for molecular testing." (PMID 37727007, 2023). "A pleural biopsy demonstrated malignant neoplasia with characteristics of adenocarcinoma, and immunohistochemistry was positive for thyroid transcription factor 1 (TTF-1)." (PMID 37503465, 2023). "These tumors also express TTF1, the adenocarcinoma marker and Tdtomato, the lineage label for type II cells." (PMID 37882674, 2023). "Adenocarcinoma is more heterogeneous and neoplastic cells are shown with abundant vacuolated cytoplasm, while is TTF‐1 and Napsin A strongly positive." (PMID 37684618, 2023). "For PFS and OS, a univariable analysis showed that both PFS and OS were significantly better in patients with the histological subtype of adenocarcinoma and patients who were TTF-1-positive." (PMID 36614938, 2022). "Cellblock confirmed the presence of adenocarcinoma of pulmonary origin, positive for thyroid transcription factor 1 (TTF-1)." (PMID 35652760, 2022). "Immunofluorescence showed that PDTs formed with adenocarcinoma cells contained TTF-1 positive cells." (PMID 35625840, 2022). "To further characterize the organoids, we performed immunohistochemistry and immunofluorescence analysis of two adenocarcinoma markers, thyroid transcription factor (TTF-1), Napsin A, as well as the epithelial marker panCK." (PMID 36712673, 2022). "In this study, we limited our analysis to adenocarcinoma to keep the histological background as similar as possible, which reduced the effect of confounding factors when evaluating the significance of TTF‐1 expression." (PMID 35808895, 2022). "The immunohistochemical analysis, using tissue microarrays of 866 NSCLC including 364 adenocarcinoma, showed a weak positive correlation between TTF‐1 and PD‐L1 expression." (PMID 35808895, 2022). "Overall, TTF-1-diffuse/Napsin A-negative (or weak) profile should raise a consideration of NEC (small cell or large cell) since most adenocarcinomas with robust TTF-1 expression are also strongly positive for Napsin A, but this is not invariable." (PMID 34663914, 2022). "TTF-1 has been shown to be a sensitive and highly specific marker of adenocarcinomas of pulmonary origin, in tissue biopsies and cytological preparations." (PMID 33975638, 2021). "Double staining of TTF-1 and napsin A has been proposed to increase the sensitivity and specificity of pulmonary-originated adenocarcinomas." (PMID 33975638, 2021).
adenocarcinoma (continued). "Bronchoscopic biopsy and IHC analysis revealed a poorly differentiated adenocarcinoma with positive expression of Napsin A, TTF‐1, CK7 and ALK (Ventana)." (PMID 34541785, 2021). "TTF-1 is expressed in the epithelial cells of the thyroid gland and lung, while adenocarcinomas are malignant transformations evolved from these cells." (PMID 33975638, 2021). "The patient went through dissection of the inguinal LN confirmed by pathologic testing to be a TTF1-positive adenocarcinoma lesion." (PMID 34298855, 2021). "The TRU-type adenocarcinoma is characterized by TTF-1 (thyroid transcription factor-1) expression and EGFR (epidermal growth receptor factor) mutations." (PMID 34679600, 2021). "First, the pathology of the intracranial cancer was adenocarcinoma and the CK, TTF1 and Napsin A were all positive in IHC." (PMID 33546082, 2021). "The patient was treated as NSCLC according to the NCCN guidelines for CUP: localized adenocarcinoma, mediastinal clinical presentation, TTF-1 positivity, and age of ≥50 years." (PMID 33101670, 2020). "We examined the expression of two adenocarcinoma markers, thyroid transcription factor (TTF-1) and Napsin A, as well as luminal epithelial marker cytokeratin 7 (CK7)." (PMID 32771979, 2020). "During his admission, he underwent thoracenteses that identified rare atypical cells suggestive of adenocarcinoma with lung primary (TTF-1 positive, Napsin A positive, mucicarmine cytochemistry negative)." (PMID 32560187, 2020). "In our patient, we treated CUP as NSCLC due to adenocarcinoma localized to the mediastinum, TTF-1 positivity, and age higher than 50 years." (PMID 33101670, 2020). "It is worth noting that a different degree of TTF1 positivity has been described for adenocarcinomas, depending on the clone used (for example, the 8G7G3/1 antibody shows higher specificity and lower sensitivity than other clones)." (PMID 31598903, 2020). "These two datasets were used because immunohistochemical analysis showed that these tumors are not only positive for TTF1 (a typical adenocarcinoma marker), but also for P63 and CK5 (typical SCC markers)." (PMID 31248101, 2019). "In the subgroup of wild-type EGFR adenocarcinoma patients, TTF-1 positivity was also a good prognostic indicator for OS and progression-free survival (PFS) after first-line cytotoxic chemotherapy." (PMID 31196060, 2019). "Collectively, it should be noted that a significant number of SqCCs or adenocarcinomas show a positivity for TTF-1 (clone SPT24) or TP63, respectively." (PMID 29538329, 2018). "IHC confirmed positivity for p40 and p63 and negativity for TTF-1 and napsin A; however, an analysis of cancer cells from plural effusion showed adenocarcinoma, with positive staining for TTF-1." (PMID 29844868, 2018). "While performing a differential diagnosis between adenocarcinoma and SqCC using an anti-TTF-1 antibody, a clone of the antibody should be paid attention to." (PMID 29538329, 2018). "But in our series, we found several patients were TTF-1+ (3 AISs, 3 MIAs, 4 lepidic adenocarcinomas), which needed further study." (PMID 29296178, 2017). "Nevertheless, we found that in early stage adenocarcinomas, the characteristics between TTF-1+ group and TTF-1− group were similar, even the patterns of recurrence (p = 0.771)." (PMID 29296178, 2017). "Both were positive for TTF-1 and napsin A. The adenocarcinoma in the left lower lobe had predominant acinary but also micropapillary and lepidic growth on biopsy." (PMID 28347348, 2017). "Totally, 126 adenocarcinomas with TTF-1− and 2687 adenocarcinomas with TTF-1+ were subjected to the study." (PMID 29296178, 2017). "For RFS, high CD73 expression (HR, 2.27; 95% CI, 1.47–3.51) was an independent unfavorable prognostic marker, after adjusting for age, sex, smoking status, stage, adjuvant chemotherapy, mutant EGFR expression, TTF-1 expression, and adenocarcinoma subtypes." (PMID 28060732, 2017).
adenocarcinoma (continued). "Immunostains for gastrointestinal tract markers were essential and other markers like TTF-1 were also applied to exclude adenocarcinoma from respiratory system." (PMID 27221036, 2016). "Previous studies have shown that high TTF-1 expression predicted better prognosis and it can be an independent predictor of favorable prognosis in adenocarcinoma patients." (PMID 27992557, 2016). "In the subtypes of NSCLCs, the expression of TTF-1 in adenocarcinomas is significantly higher than that for squamous cell carcinomas." (PMID 27992557, 2016). "Protein expression of adenocarcinoma markers TTF-1 and Napsin A and squamous markers CK5 and P40 were investigated in the Lund cohort and the public LCNEC cohort (TTF-1 only)." (PMID 26124082, 2015). "In contrast, adenocarcinoma shows significant expression heterogeneity for all ‘squamous markers’; only diffuse TTF-1 expression is specific for adenocarcinoma." (PMID 24748366, 2014). "The histology analysis of the biopsy and surgical specimen favored an adenocarcinoma with immunostaining positive for TTF1 and thyroglobulin (Tg)." (PMID 23509641, 2013). "Histopathology showed papillary structures, colloid material, psamomma bodies and adenocarcinoma cells positive for TTF-1 and thyroglobulin, confirming a metastatic PTC." (PMID 23724969, 2013). "After 9 months she presented with diffuse goiter initially believed to be a solitary metastatic lesion as it was positive for adenocarcinoma of lung origin on histopathological exam with TTF-1 positivity." (PMID 24455357, 2013). "These can then go on to progress to become malignant adenocarcinomas that typically express positivity for CK-7 and TTF-1." (PMID 26029517, 2013). "Co-expression of TTF-1 and surfactant proteins is usually detected in health adult bronchioles, alveolar epithelum, and well-differentiated differentiated adenocarcinoma." (PMID 23587094, 2013). "Of the 44, 40 were TTF-1 positive, while in 6, the foci of adenocarcinoma co-expressed TTF-1 and p63." (PMID 23922677, 2013). "In contrast, β-catenin (−/−) knock down leads to down-regulation of differentiated peripheral alveolar epithelial cells, which are the origin of the peripherally derived TTF1-positive adenocarcinomas." (PMID 23224985, 2013). "Cytological and immunohistological features were consistent with adenocarcinoma, with positive thyroid transcription factor-1 (TTF-1) and PAX8 suggesting metastatic thyroid carcinoma." (PMID 23724969, 2013). "Of note, SCLC had identical p63/TTF-1 expression profile as adenocarcinoma, but application of standard morphologic criteria and addition of neuroendocrine markers was sufficient for accurate classification." (PMID 21776344, 2011). "In the case of adenocarcinoma, diagnosis was supported by expression of TTF-1, CK7 or BerEP4 and negativity for CK5 and p63." (PMID 21949883, 2011). "In case of adenocarcinomas, 90.2% showed positive expression of TTF-1 and 74.2% were positive for MAdL." (PMID 21811254, 2011). "This study investigated the relation between positive thyroid transcription factor 1 (TTF1) staining and survival of patients affected by primary adenocarcinoma (ADC) of the lung." (PMID 16052216, 2005). "Combining napsin and TTF-1 resulted in a higher sensitivity for adenocarcinoma (89.7% (35 out of 39)) whereas the specificity was the same as TTF-1 alone (76.7%)." (PMID 12698189, 2003). "Sp-A, Sp-B and TTF-1 were expressed in adenocarcinomas but the expression was also observed in other types of lung tumours." (PMID 12698189, 2003). "Metastatic adenocarcinomas are often tested for TTF-1 expression to identify their primary site." (PMID 41635529, 2026). "TTF1 is considered a highly useful marker for identifying lung origin in adenocarcinomas." (PMID 40751531, 2025).
adenocarcinoma (continued). "By incorporating PKP1 into algorithm-driven panels that integrate IHC, genomic, and morphologic features (e.g., alongside PD-L1 for immune context, TTF-1/Napsin A for adenocarcinoma, and p63 for SCC), its contribution can be dynamically weighted to enhance diagnostic accuracy." (PMID 41458151, 2025). "Notably, only two of the tumors with dual TTF-1 and Napsin A expression that were exclusively adenocarcinomas of the upper gastrointestinal tract, were CDX2 positive." (PMID 40564811, 2025). "Adenocarcinoma cells show positive staining for TTF1, Napsin A, monoclonal CEA, and CK-7." (PMID 40091315, 2025). "Our analyses demonstrate that clinical features such as younger age, never-smoking status, TTF1 positivity, and adenocarcinoma histology are strongly associated with small primary tumors that present with early distant metastases." (PMID 41374930, 2025). "Adenocarcinoma, the most common subtype, is often peripheral, commonly found in non-smokers, and expresses markers like TTF-1, Napsin A, and CK7, with potential mutations in EGFR and ALK that can be targeted with specific therapies." (PMID 40827171, 2025). "This dropped the sensitivity of TTF1 in well-differentiated adenocarcinomas to 86.6%." (PMID 39584166, 2024). "Pathology from an RLL lung biopsy indicates TTF1 positive adenocarcinoma with a PD-L1 TPS of 60% and no actionable mutations identified through NGS." (PMID 39590145, 2024). "Indeed, in this study, the TTF-1-positive group exhibited a significantly higher proportion of adenocarcinomas and a smaller proportion of non-adenocarcinoma NSCLCs than the TTF-1-negative group." (PMID 39076994, 2024). "Previous research suggested that TTF‐1 and Napsin A, both of which had a sensitivity of about 80% and were more easily evaluated as a nuclear stain, were well‐established markers for the identification of adenocarcinoma differentiation." (PMID 37215977, 2023). "Thyroid transcription factor 1 (TTF-1) is a well-known marker for adenocarcinoma." (PMID 37513898, 2023). "While TTF1 is specific, it is less sensitive for adenocarcinoma." (PMID 35468849, 2022). "Four tumors were positive for TTF-1 expression and were re-classified as adenocarcinomas." (PMID 35329826, 2022). "In a differential diagnosis using immunohistochemical staining, TTF-1 is a specific marker of the lung and thyroid gland and is also used to identify the primary lesion of adenocarcinoma of unknown primary." (PMID 36459241, 2022). "In addition, these TTF-1 positive cells expressed Ki67, indicating that these TTF-1 positive adenocarcinoma cells were proliferating." (PMID 35625840, 2022). "However, the bronchial brushing and washing demonstrated malignant cells consistent with adenocarcinoma with weak TTF-1 positive staining." (PMID 32560187, 2020). "Six of them showing CK7+ and CK5/6− immunostaining were diagnosed as “TTF-1+ p63+ adenocarcinoma”." (PMID 31935792, 2020). "Some data suggest that TTF-1 might promote carcinogenesis by enhancing cell proliferation, namely at least adenocarcinoma." (PMID 31196060, 2019). "CK8/18, TTF1 and NapsinA were specific clinical diagnosis indexes for adenocarcinoma." (PMID 29788985, 2018). "TTF1 expression decreases in poorly differentiated (~50%) compared with well-differentiated (~100%) adenocarcinomas, diminishing the sensitivity of this marker to identify the pulmonary origin of a poorly differentiated adenocarcinoma." (PMID 29621151, 2018). "In contrast with NSCLC, PD-L1 expression in PSCGCC is related to the presence of adenocarcinoma markers such as TTF-1 and/or Napsin A. Another hope for patients with lung SC is the relatively higher frequency in this subtype of exon 14 skipping of MET (hepatocyte growth factor receptor gene)." (PMID 28671973, 2017). "TTF1 IHC is a diagnostic biomarker used routinely in the clinic to discriminate primary lung tumors versus metastases from other sites and to determine histologic subtype (e.g., SCLC, adenocarcinoma, squamous)." (PMID 29088717, 2017).
adenocarcinoma (continued). "Among adenocarcinomas with TTF-1−, the major subtype was acinar-predominant adenocarcinomas, followed by invasive mucinous and papillary subtypes while acinar, papillary and minimally invasive adenocarcinoma were in the majority among adenocarcinomas with TTF-1+." (PMID 29296178, 2017). "Indeed, the SCC marker DNp63 was significantly downregulated, and the adenocarcinoma markers TTF1 and napsin A were markedly upregulated, suggesting that silencing of S100A7 attenuated lung ADC to SCC transdifferentiation." (PMID 28177901, 2017). "TTF-1-positive adenocarcinomas exhibit a high degree of cytological similarity to, and may arise from, type II pneumocytes or Clara cells." (PMID 27575252, 2016). "A few ALK-rearranged tumors coexpressed p63 and TTF1 in the adenocarcinoma component." (PMID 26575266, 2015). "In a large cohort of 1478 NSCLCs, ROS1 expression was correlated with better survival and specific features such as low T stages, TTF1 and napsin expression, and certain histomorphological adenocarcinoma patterns (lepidic, acinar, and solid), although there is also a contradictory data." (PMID 26475437, 2015). "In our LC cohort, 24 tumors (59%) were positive by immunohistochemistry for TTF-1/Napsin A (referred to as adenocarcinoma-like), 5 tumors (12%) were CK5/P40 positive (squamous-like), whereas 12 tumors (29%) did not express any of these IHC markers (marker null cases)." (PMID 26124082, 2015). "TTF1 immunostaining was detected in 17/25 (68 %) adenocarcinoma brain metastases." (PMID 23224985, 2013). "It is worth mentioning that coexpression of TTF-1 and p63 can be seen in adenocarcinomas." (PMID 21776344, 2011). "Evidence of antibodies to TTF-1 may identify the lung as the primary site of origin in adenocarcinoma with unknown primary." (PMID 18667060, 2008). "Interestingly, TTF-1 expression in adenocarcinoma is inversely correlated with expression of maspin, which we have previously shown to be tightly restricted to basal cells of the bronchial epithelium in normal lung." (PMID 15467767, 2004). "However, enteric adenocarcinomas occasionally show focal TTF-1 expression and EGFR mutations, suggesting that some enteric adenocarcinomas may be phenotypically altered from TRU-type adenocarcinomas." (PMID 38710944, 2025). "Respectively, the differential diagnostic of primary adenocarcinomas originating from lung cells from metastatic adenocarcinomas made of the malignant cells traveling from distant organs and tissues requires the panel of three antibodies directed to CK7, CK20, and TTF1." (PMID 39329988, 2024). "Pathology from EBUS indicated adenocarcinoma (TTF1 positive) with a RET fusion; PD-L1 was unknown." (PMID 39590145, 2024). "Notably, in a study, it was found that the preferential reactivity of p63 in TTF-1-positive adenocarcinoma was seen to have EML4-ALK translocation, implying that this expression might not be merely aberrant." (PMID 39070322, 2024). "The different frequency of EGFR and ALK subtypes between TTF-1 positive and TTF-1 negative subtypes might be linked to the fact that TTF-1 negative tumors in biopsies represent a group enriched in rare adenocarcinomas subtypes." (PMID 35885495, 2022). "In particular, TTF-1, member of the NKx2 homeodomain transcription factor family, is expressed in the lung and thyroid and widely used in surgical pathology, also for determining if an adenocarcinoma of unknown primary is of pulmonary origin." (PMID 23663245, 2013). "Adenocarcinoma originating from the anal gland with immunohistochemical expression of GATA3 and TTF-1 (ACAGGT) is a rare entity." (PMID 41907615, 2026). "Immunohistochemically, HAL is characterized by strong and diffuse HepPar1 expression, positivity for adenocarcinoma markers such as MOC31, and cytoplasmic immunoreactivity for TTF-1." (PMID 42096087, 2026). "In differentiating SCC from adenocarcinoma, especially in the lung and salivary glands, CK7, TTF-1, and napsin A serve as key markers." (PMID 40427131, 2025).